NMUR2 (neuromedin U receptor 2)
Diseases named in the same sentence as NMUR2 in open-access papers (continued):
Sharing a sentence is not in itself a finding about the gene and the disease.
renal carcinoma (1 paper, 2011). A carcinoma arising from the epithelium of the renal parenchyma or the renal pelvis. "To determine whether renal cancer cells might respond to NMU we first examined expression of the receptors NMUR1 and NMUR2." (PMID 21791076, 2011).
cancer (9 papers, 2013 to 2024). A tumor composed of atypical neoplastic, often pleomorphic cells that invade other tissues. "TCGA data analysis showed that high NMUR2 levels are characteristic of cancers with low differentiation and increased invasiveness, as represented by decreased CDH1 expression and increased MMP1 expression." (PMID 34493299, 2021). "Further studies are needed to confirm the involvement of NMUR2 in mechanical hypersensitivity in humans, including patients with cancer." (PMID 31196165, 2019). "NMU has been shown to play an important role in cancer through NMUR1 or NMUR2 dependent pathway." (PMID 39055918, 2024). "Finally, we showed that NMU induced an invasive phenotype in NMUR2-positive cancer cells." (PMID 34493299, 2021). "NMU binds to the specific receptors NMUR1 or NMUR2, which are unevenly distributed on different types of CRC cells and, as we showed, are related to inducing cancer cell motility." (PMID 36482448, 2022). "Taken together, these results suggest that high NMUR2 and NMU expression correlates with decreased cancer differentiation and increased invasive potential." (PMID 34493299, 2021). "To characterize NMUR2-positive CRC samples, we analysed the level of CDH1 (E-cadherin), a functional marker of cancer cell differentiation, and MMP1, a mediator of primary tumour invasion, in groups with various NMUR2 expression levels." (PMID 34493299, 2021). "In contrast NMUR2 was expressed in all subtypes but basal-type carcinomas almost completely lacking NMUR2 expression (median expression = 0)." (PMID 28423716, 2017). "Our CRC cell clone studies showed that regardless of the parental cell phenotype, NMU overexpression in cells expressing NMUR2 enhances the metastatic potential of the cells by increasing their mobility and invasiveness via ERK1/2 kinase activation, as previously shown for other cancers." (PMID 34493299, 2021). "TCGA data analysis enabled us to report, for the first time, higher NMU and NMUR2 expression in CRC tissues than in normal epithelium and, similar to other cancer types, a noticeable trend of lower overall survival of patients with high NMU expression in their cancer tissues." (PMID 34493299, 2021). "In addition, NMUR2S also co-exists with NMUR2 and/or NMUR1 in many other human cancer cell lines." (PMID 26317338, 2015).
tumor (6 papers, 2017 to 2025). "Other membrane proteins, such as GPCRs (e.g., GRM6, GPR37L1, NMUR2), are highly expressed to mediate growth and survival signaling, amplify tumor proliferation signals, and prevent apoptosis." (PMID 41440381, 2025). "In contrast, NMUR2 expression was found to be significantly increased in paired samples (n = 16) and tumours in the T2-T4 stages, but it was barely detectable in other samples." (PMID 34493299, 2021). "In the NMUR2-positive SKBR3 tumor model, we indeed observed a slight but reproducible decrease in median cell-Matrigel adhesion of NMU clones by 11.3 % compared to mock controls (P < 0.05)." (PMID 28423716, 2017). "NMU/NMUR2 expression levels could be useful for more accurate clinical staging and identifying tumours with invasive potential." (PMID 34493299, 2021). "Considering that the current results regarding NMU receptor signalling do not discriminate between NMUR1 and NMUR2 signal transduction, it is interesting that metastatic tissues express more NMUR1 but pancreatic primary tumours “invest” in NMUR2 overproduction." (PMID 31492042, 2019). "Meanwhile, the expression level of hub genes BDKRB1, NMUR2, PMCH, and SAA1 in pRCC tissues was significantly positively correlated with tumor stage, lymph node metastasis, and the histopathology grade of pRCC." (PMID 36785669, 2023).
NMUR2 also shares sentences with these, for which no sentence is quoted: glioblastoma (1 paper); inflammation (1); lymph node metastasis (1); metabolic disorders (1); periodontitis (1); substances of abuse (1).